NPAS4 (neuronal PAS domain protein 4)
Diseases named in the same sentence as NPAS4 in open-access papers (continued):
Sharing a sentence is not in itself a finding about the gene and the disease.
cognitive deficits (12 papers, 2012 to 2025). "We used a developmental model of NMDA receptor dysfunction to assess for specific changes in Npas4 expression in the PFC within the context of cognitive deficits associated with dysfunction of the prefrontal PV system." (PMID 30792384, 2019). "We observed that the cognitive deficits and hyperactivity induced by neonatal ketamine were associated with a downregulation of Npas4 expression specifically in PV+ neurons." (PMID 30792384, 2019). "Cognitive impairments are associated with decreased Npas4 mRNA expression in the mouse frontal cortex." (PMID 29093669, 2017). "After chronic stress, NPAS4 mRNA is significantly decreased in the hippocampus of juvenile mice, and these NPAS4-deficient juveniles developed cognitive deficits in adulthood." (PMID 28503137, 2017). "Regarding Npas4 significance for maintaining excitation-inhibition equilibrium, it can be presumed that Npas4 deficiency would result in cognitive deficits." (PMID 25785202, 2015). "The neurological deficit and behavior were evaluated and NPAS4 mRNA expression was measured by semi-quantitative reverse transcription-polymerase chain reaction; furthermore, the association with cognitive impairment was analyzed." (PMID 24669275, 2014). "Collectively, our findings and extant literature indicate that Npas4 may be critically implicated in the cognitive deficits associated with AD." (PMID 38958450, 2024). "Specifically, we aimed to determine whether Npas4 downregulation could contribute to prefrontal PV+ neurons dysfunction and thereby could be a molecular mechanism underlying cognitive deficits in neurodevelopmental disorders." (PMID 30792384, 2019). "Evidence from our laboratory indicate that Npas4 deficiency in mice leads to severe behavioral impairments that are reminiscent of those observed in schizophrenia, including social, sensori-motor gating and cognitive deficits, and hyperactivity." (PMID 30792384, 2019). "Reduced levels of NPAS4 mRNA in the hippocampus of PSD rats may be a significant factor in the biological mechanisms underlying cognitive impairment." (PMID 24669275, 2014). "have also been candidates in studies of human pathophysiology in mental disorders, including schizophrenia, bipolar and cognitive disorders, and are up (NPAS4) and down-regulated (HTR2C) in the adult group of bulls." (PMID 35032285, 2022). "More specifically for NPAS4, it has been demonstrated that Npas4+/− mice exposed to juvenile stress present with cognitive deficits in adulthood when compared to heterozygotes that were stressed in adulthood or not at all58." (PMID 33758288, 2021). "Our findings implicate for the first time the transcription factor Npas4 to prefrontal PV+ neurons dysfunction and cognitive deficits as seen in schizophrenia and other neurodevelopmental disorders." (PMID 30792384, 2019). "As NPAS4 is significant in inhibitory post-synaptic development and stress-induced hippocampal damage, the changes in NPAS4 expression were investigated and the cognitive impairment was demonstrated by behavioral changes in the rat PSD model." (PMID 24669275, 2014). "Our novel findings reveal that Npas4 could be part of the cascade of molecular events by which oxidative stress leads to PV+ neurons dysfunction in schizophrenia, and thereby to cognitive deficits." (PMID 30792384, 2019). "In conclusion, our data support the idea that the level of expression of Npas4 within PV+ neurons could be a major molecular contributor to the cognitive deficits observed in several neurodevelopmental disorders marked by PV+ neurons dysfunction." (PMID 30792384, 2019). "Finally, we used a genetic approach to assess the extent to which Npas4-dependent PV+ neurons dysfunction is sufficient to replicate the behavioral and cognitive impairments observed in our developmental mouse model of schizophrenia." (PMID 30792384, 2019).
cognitive deficits (continued). "In conclusion, NPAS4 may be an important regulatory transcription factor in the cognitive impairment process, which directly or indirectly affects cognitive function via BDNF." (PMID 24669275, 2014). "We observed that Npas4 null mice display several behavioral impairments, including hyperactivity in a novel environment, disruption of prepulse inhibition, social interaction deficits and cognitive impairments." (PMID 23029555, 2012). "In the present study, the deregulation of inhibitory synapses induced by the absence of Npas4 seems to be responsible for the deficit in PPI and for the other cognitive impairments observed in Npas4-KO mice; however, the exact mechanism is not yet known." (PMID 23029555, 2012). "Precisely, mice lacking Npas4 display social and cognitive impairments similar to those observed in autism or schizophrenia, and hyperactivity and deficit in pre-pulse inhibition, which are endophenotypes of schizophrenia." (PMID 23029555, 2012). "While changes in Npas4 expression within PV+ cells could contribute to cognitive impairments, the effects of developmental NMDA receptor hypofunction on the hyperactive phenotype we observed is likely to be independent of Npas4-induced dysfunction of PV+ neurons." (PMID 30792384, 2019).
schizophrenia (10 papers, 2012 to 2023). A major psychotic disorder characterized by abnormalities in the perception or expression of reality. "For example, rescue of disrupted Npas4 expression to the prefrontal cortex of mice with schizophrenia-associated 16p11.2 microduplications led to a rescue of neuronal excitatory/inhibitory balance, and behavioral phenotypes, in this mouse model." (PMID 34588960, 2021). "Moreover, NPAS4 has been potentially implicated with schizophrenia and autism, due to its critical involvement in maintaining a balance between excitation and inhibition and thereby contributing to the formation of inhibitory synapses." (PMID 36674969, 2023). "Finally, it is interesting to note that the location of the Npas4 gene in the human genome (chromosome 11, locus 11q13) has been associated with schizophrenia in a genome-wide linkage disequilibrium survey in a Japanese population." (PMID 23029555, 2012). "Also, similar social dysfunctions to the ones observed in Npas4-KO mice have already been observed in mice characterized by alterations in the inhibitory pathways such as the TgNL2.6 strain or in neuregulin 1, the schizophrenia risk gene, knockout mice." (PMID 23029555, 2012). "More importantly, their results in this mouse model were corroborated with human postmortem tissue of schizophrenia patients, which also showed downregulation of Npas4 in the frontal cortex." (PMID 30792384, 2019). "Recently, studies have highlighted the potential involvement of the brain-specific transcription factor Npas4 to the molecular abnormalities and symptoms of schizophrenia." (PMID 30792384, 2019). "Our research confirm these findings by employing a different developmental mouse model of schizophrenia, which resulted in a similar reduction in Npas4 expression." (PMID 30792384, 2019). "We first used a developmental mouse model of schizophrenia to induce dysfunction of prefrontal PV+ interneurons and behavioral anomalies, and to assess changes in Npas4 expression within this context." (PMID 30792384, 2019). "Using a developmental mouse model of schizophrenia, we report for the first time a PV+ neuron-specific downregulation of the brain-specific transcription factor Npas4 following neonatal exposure to ketamine." (PMID 30792384, 2019). "Further studies will aim at defining the mechanism of action of Npas4 and identifying the Npas4-mediated signaling cascade in the normal brain as well as in pathological conditions such as schizophrenia and autism." (PMID 23029555, 2012). "Npas4 is important for inhibitory synapse development in the prefrontal cortex during adolescence, implicating Npas4 dysregulation in disorders such as schizophrenia." (PMID 35955487, 2022). "Moreover, suppression of Npas4 expression in PV+ interneurons phenocopies behavioral deficits seen in developmental mouse models of schizophrenia." (PMID 34588960, 2021). "Such an assessment will establish whether Npas4 downregulation leads to similar changes within PV+ neurons and prefrontal circuits to those observed in schizophrenia." (PMID 30792384, 2019). "Here, we particularly aim to characterize the scope of Alachkar’s findings and investigate whether prefrontal downregulation of Npas4 is a generalized characteristic in rodent-based models of schizophrenia." (PMID 30792384, 2019). "To determine the extent to which downregulation of Npas4 within PV+ neurons could contribute to the behavioral abnormalities observed in the neonatal exposure ketamine model of schizophrenia we used a genetic approach." (PMID 30792384, 2019). "However, there are few human variants in NPAS3 and none in NPAS4 that have been associated with schizophrenia or neurodevelopmental disorders." (PMID 33758288, 2021). "Our results suggest that Npas4 may play a major role in the regulation of cognitive and social functions in the brain with possible implications for developmental disorders such as schizophrenia and autism." (PMID 23029555, 2012).
schizophrenia (continued). "Not surprisingly, NPAS4 null mice are hyperactive, prone to seizures, and display several defects in social anxiety and cognitive impairments similar to those observed in autism and schizophrenia." (PMID 24465693, 2014).
autism (9 papers, 2012 to 2026). Persistent deficits in social interaction and communication and interaction as well as a markedly restricted repertoire of activity and interest as well as repetitive patterns of behavior. "Npas4 dysfunction has been suggested to be involved in autism, bipolar disorder, and cognitive disorders." (PMID 33772088, 2021).
Stroke (9 papers, 2013 to 2025). Sudden impairment of blood flow to a part of the brain due to occlusion or rupture of an artery to the brain. "Npas4 knock-out mice also exhibited higher levels of the pro-inflammatory cytokines IL-6 and TNF-α post-stroke, and stroke-induced upregulation of Npas4 was found in brain regions linked to emotion and cognition." (PMID 33335473, 2020). "Npas4 deficiency increases the susceptibility to neuronal damage from a variety of insults, suggesting Npas4 modulation as a potential therapeutic strategy against multiple conditions such as learning deficits, addiction, stroke, and AD." (PMID 33335473, 2020). "Interestingly, our laboratory has also shown that Npas4 deficiency resulted in a significant increase in the number of activated microglia and astrocytes 96 h after the induction of stroke." (PMID 26690124, 2015). "Long-term fluoxetine administration, indeed, not only induces NPAS4 expression, but also has been proved successful in promoting the functional recovery from stroke in humans, which is a major cause of long-term disability for which there is currently no clinical treatment." (PMID 24024041, 2013). "Overexpression of several IEGs including the transcription factors neuronal PAS domain protein 4 (Npas4) and activating transcription factor 3 (Atf3) in the mouse hippocampus via AAVs protects against stroke-induced neuronal damage." (PMID 39482558, 2025). "NPAS4 deficiency in mice results in an increase in activated microglia and astrocytes as well as increased protein levels of IL-6 and TNF-α after stroke." (PMID 37938766, 2024). "Our laboratory has shown that there was a robust but transient induction of Npas4 protein that peaked 1.5 h following the induction of stroke before progressively declining to baseline levels by 12 h post-stroke." (PMID 26690124, 2015). "A microarray study of gene expression following stroke showed that Npas4 was one of the most profoundly upregulated genes in the rat brain following 2 h of middle cerebral artery occlusion (MCAo)." (PMID 26690124, 2015). "The protective effect of Npas4 was further investigated in vivo using a photochemically-induced stroke model in mice." (PMID 26690124, 2015). "Understanding how ischemic lesion size in stroke may be reduced through modulation of Npas4-dependent apoptotic and inflammatory pathways could lead to the development of new stroke therapies." (PMID 26690124, 2015). "Recently, our laboratory has demonstrated that Npas4 indeed has a neuroprotective role in ischemic stroke and that Npas4 might be involved in modulating the post-stroke inflammatory response." (PMID 26690124, 2015). "This review summarizes the current knowledge of the roles that Npas4 may play in stroke and describes the possible cellular and molecular mechanisms by which Npas4 links the neuroinflammatory and ischemic processes." (PMID 26690124, 2015). "In addition, this stroke-induced upregulation of Npas4 was found not only in the ischemic penumbra but also detected in brain regions outside of the penumbra, more specifically in the corticolimbic system that is critically linked to emotion and cognition." (PMID 26690124, 2015). "We have noted that Npas4−/− mice had both increased IL-6 and TNF-α expression post-stroke." (PMID 26690124, 2015).
Cerebral ischemia (8 papers, 2014 to 2024). Restriction of arterial blood supply to the brain associated with insufficient oxygenation to support the metabolic requirements of the tissue. "For example, NPAS4 encodes for a transcription factor whose expression is induced in various brain insults, including cerebral ischemia." (PMID 36707762, 2023). "Global cerebral ischemia, caused by clamping of the common carotid arteries for 10 min, produced a much more sustained response in Npas4 mRNA expression." (PMID 26690124, 2015). "The study also found that using OGD, knockout of Npas4 in cultured neurons resulted in increased susceptibility to cell death and also found that Npas4-/-mice had significantly larger lesion areas than wild-type mice after induction of cerebral ischemia and neurodegeneration." (PMID 36157893, 2022). "A significantly larger lesion size and more severe neurodegeneration in Npas4−/− mice following cerebral ischemia modeling were reported, thus confirming the neuroprotective role of NPAS4 in ischemic stroke." (PMID 37176030, 2023). "NPAS4 indeed has a neuroprotective role in cerebral ischemia, probably being involved in cell death and inflammatory response modulation." (PMID 36707762, 2023). "Npas4 has neuroprotective effects against cerebral ischemia, neurodegeneration, and neuroinflammation." (PMID 33772088, 2021). "Studies on the effects of cerebral ischemia and neuronal activity on Npas4 expression have been reviewed." (PMID 33335473, 2020). "Neuronal Per-Arnt-Sim domain protein 4 (Npas4) is an activity-dependent transcription factor whose expression is induced in various brain insults, including cerebral ischemia." (PMID 26690124, 2015). "We found a significantly larger lesion size and increased neurodegeneration in Npas4−/− mice when compared with wild-type mice following the induction of cerebral ischemia, confirming that Npas4 is neuroprotective in ischemic stroke." (PMID 26690124, 2015). "Npas4−/− mice subjected to focal cerebral ischemia showed a significant decrease in the number of apoptotic cells in the lesion core as compared to wild-type mice as seen by a reduction in both TUNEL staining and the number of cells expressing apoptosis-inducing factor (AIF)." (PMID 26690124, 2015). "NPAS4 is gradually normalized via its own feedback loop, which may explain why BDNF mRNA expression is transiently increased following cerebral ischemia." (PMID 24669275, 2014).
ischemic stroke (7 papers, 2015 to 2025). A stroke disorder caused by obstruction of blood flow to the brain, due to thrombotic (local blood clot formation) or embolic (due to a blood clot or other material traveling from another site) event. "More and more studies have revealed that NPAS4 plays an important role in neurological diseases such as ischemic stroke, autism, depression, cognitive disorders, etc.." (PMID 37176030, 2023). "More importantly, upregulated Npas4 expression has been reported in various brain insults, including focal and global ischemic stroke." (PMID 26690124, 2015). "Similarly, it has been reported that NPAS4 was upregulated in a series of brain damages such as focal and global ischemic stroke." (PMID 37176030, 2023). "Recently, it was demonstrated that Npas4 indeed has a neuroprotective role in ischemic stroke and that Npas4 might be involved in modulating the cell death pathway and inflammatory response." (PMID 26690124, 2015). "Among them, there may be previously listed Fos, Junb, Jak2, Npas4, Egr2 and other proteins, which may help to validate some key signaling pathways after peptide treatment at the protein level and reveal the potential effects of peptides on ischemic stroke." (PMID 39767736, 2024). "Moreover, recent studies suggest that NPAS4 may exert neuroprotective effects in ischemic stroke via regulation of cell death and of the inflammatory response." (PMID 29556248, 2018). "Therefore, harnessing the multidimensional neuroprotective capacity of Npas4 could limit progressive neurodegeneration and neuroinflammation, potentially providing new strategies for the treatment of ischemic stroke." (PMID 26690124, 2015).
ischemia (5 papers, 2014 to 2020). A hypoperfusion of the BLOOD through an organ or tissue caused by a PATHOLOGIC CONSTRICTION or obstruction of its BLOOD VESSELS, or an absence of BLOOD CIRCULATION. "Npas4 is neuroprotective after ischemia which occurs transiently with minimal damage each time the hibernator arouses from torpor." (PMID 33536943, 2020). "Npas4 is an activity-dependent transcription factor whose expression is robustly and transiently upregulated in the brain during the acute phase of ischemia." (PMID 26690124, 2015). "Recently, using oxygen and glucose deprivation (OGD) as an in vitro model of ischemia, we also found that Npas4 transcript levels were upregulated in primary mouse cortical neurons." (PMID 26690124, 2015). "In this review, we summarize the current knowledge of the roles that Npas4 may play in neuroinflammation and ischemia." (PMID 26690124, 2015). "NPAS4 combines with ARNT2 to regulate the expression of BDNF, with consequent neuroprotective effects on brain injury and ischemia." (PMID 24669275, 2014).
memory impairment (5 papers, 2014 to 2024). "Though deletion of Npas4 is not lethal, mice lacking the Npas4 gene display numerous deleterious phenotypes that negatively impact upon the animal’s fitness including a shortened lifespan, vulnerability to seizure, memory impairments and sensorimotor deficits." (PMID 25538572, 2014).
bipolar disorder (4 papers, 2014 to 2023). A disorder of the brain that causes unusual shifts in mood, energy, activity levels and the ability to carry out day-to-day tasks. "While protein coding variants in NPAS4 have yet to be associated with a human disorder, the region surrounding NPAS4 has been found to be deleted in a boy with intellectual disability, and a region encompassing NPAS4 has been found to be associated with bipolar disorder." (PMID 24465693, 2014).
breast cancer (4 papers, 2017 to 2021). A primary or metastatic malignant neoplasm involving the breast. "NPAS4 and CENPB, on the other hand, are both involved with breast cancer." (PMID 28607444, 2017).